CPSF2 (cleavage and polyadenylation specific factor 2)
Description:
Component of the cleavage and polyadenylation specificity factor (CPSF) complex that play a key role in pre-mRNA 3'-end formation, recognizing the AAUAAA signal sequence and interacting with poly(A) polymerase and other factors to bring about cleavage and poly(A) addition. Involved in the histone 3' end pre-mRNA processing.
Synonyms: CPSF100; KIAA1367
Tractability: PROTAC: ubiquitination databases record sites on it; its protein half-life has been measured.
Gene: Protein-coding gene on chromosome 14 (92,121,512 to 92,172,145, forward strand). Ensembl gene ENSG00000165934.
Subcellular location: Nucleus
Subcellular location (Human Protein Atlas): Nucleoplasm; Vesicles
Pathways (Reactome):
Metabolism of RNA: Processing of Intronless Pre-mRNAs; Transport of Mature mRNA Derived from an Intronless Transcript; mRNA 3'-end processing; mRNA Polyadenylation
Disease: Dengue Virus-Host Interactions
Gene expression (Transcription): RNA Polymerase II Transcription Termination
Gene Ontology:
Molecular function: protein binding; RNA binding
Biological process: mRNA 3'-end processing; mRNA 3'-end processing by stem-loop binding and cleavage; nuclear histone mRNA catabolic process
Cellular component: membrane; mRNA cleavage and polyadenylation specificity factor complex; mRNA cleavage factor complex; nucleoplasm; nucleus; glutamatergic synapse; postsynapse
Genetic constraint (gnomAD): Loss-of-function variants: 29 observed, 60.78 expected, observed/expected ratio (o/e) 0.48, 90% interval 0.35 to 0.65. The upper end of that interval is the gene's LOEUF score, 0.65, which puts it in group 2 of 6, group 1 being the genes least tolerant of losing a copy. Missense variants: 538 observed, 804.22 expected, observed/expected ratio (o/e) 0.67, 90% interval 0.62 to 0.72. Synonymous variants: 236 observed, 273.77 expected, observed/expected ratio (o/e) 0.86, 90% interval 0.77 to 0.96.
Homologues: Orthologues: chimpanzee CPSF2 (100% identical), macaque CPSF2 (99% identical), guinea pig CPSF2 (99% identical), dog CPSF2 (99% identical), pig CPSF2 (99% identical), rabbit CPSF2 (99% identical), rat Cpsf2 (98% identical), mouse Cpsf2 (98% identical), tropical clawed frog cpsf2 (92% identical), zebrafish cpsf2 (87% identical), Drosophila melanogaster Cpsf100 (55% identical), Caenorhabditis elegans cpsf-2 (46% identical). Paralogues in human: CPSF3 (19% identical), INTS11 (19% identical), INTS9 (15% identical).
Diseases named in the same sentence as CPSF2 in open-access papers:
CPSF2 is named in the same sentence as 30 diseases in open-access papers, as found by Europe PMC text mining. Sharing a sentence is not in itself a finding about the gene and the disease. The quoted sentences say what the papers report.
atherosclerosis (2 papers, 2021 to 2024). A disease characterized by the build-up of fatty material and calcium deposition in the arterial wall resulting in partial or complete occlusion of the arterial lumen. "Serum antibody levels of DIDO1, FOXJ2, and CPSF2 are useful in predicting the onset of atherosclerosis-related AIS caused by kidney failure, hypertension, and DM, respectively." (PMID 34103026, 2021). "Moreover, the levels correlated most closely with max IMT, indicating that CPSF2-Ab can mainly detect DM-caused atherosclerosis leading to AIS." (PMID 34103026, 2021). "CPSF2-Ab may reflect DM-caused atherosclerosis and the causes of cancer and atherosclerosis overlap with each other." (PMID 34103026, 2021). "For instance, the antigenic proteins of other atherosclerosis autoantibody markers, DIDO1-Abs, CPSF2-Abs, and FOXJ2-Abs, were highly expressed in the carotid atherosclerotic plaques." (PMID 38732153, 2024).
breast carcinoma (2 papers, 2021 to 2023). "Serum CPSF2-Ab levels were associated primarily with AIS and DM and partly with TIA, cCI, esophageal squamous cell carcinoma, and rheumatoid arthritis but not with AMI, CKD, CVD, colorectal carcinoma, gastric cancer, breast cancer, pancreatic cancer, Sjögren’s syndrome, SLE, or ulcerative colitis." (PMID 34103026, 2021).
COVID-19 (2 papers, 2021 to 2024). A disease caused by infection with severe acute respiratory syndrome coronavirus 2. "For example, ZNF385D and CPSF2, which are both repressed by the S1 subunit, are associated with COVID-19-related inflammation and stroke." (PMID 38674024, 2024). "On the other hand, PNMA8A/PNMAL1 was also listed among stroke candidate genes, and ZNF385D and CPSF2, which are repressed by the S1 subunit, were also associated with inflammation and stroke in relevance to COVID-19." (PMID 38674024, 2024). "CPSF2 was identified among the top-30 hub genes underlying the pathophysiological correlation between acute myocardial infarction and COVID-19." (PMID 38674024, 2024). "Moreover, CPSF2 has been identified amongst the top-30 hub genes that underlie the pathophysiological link between acute myocardial infarction and COVID-19." (PMID 38674024, 2024).
cerebral infarction (1 paper, 2021). An ischemic condition of the brain, producing a persistent focal neurological deficit in the area of distribution of the cerebral arteries. "Likewise, the antibody levels of the DIDO1, FOXJ2, and CPSF2 peptides were positively correlated with a risk of cerebral infarction: odds ratios (95% CIs) of the highest quartile were 2.66 (1.43–4.95), 2.24 (1.27–3.95), and 2.41 (1.33–4.37), respectively." (PMID 34103026, 2021).
dyslipidemia (1 paper, 2021). "Meanwhile, serum CPSF2-Ab levels were associated with DM, hypertension, and smoking habit but not with CVD or dyslipidemia." (PMID 34103026, 2021).
esophageal squamous cell carcinoma (1 paper, 2021). Esophageal squamous cell carcinoma (ESCC) is a type of esophageal carcinoma (EC) that can affect any part of the esophagus, but is usually located in the upper or middle third. "Our results showed only a slight association of CPSF2-Abs with esophageal squamous cell carcinoma (P < 0.01) but not with other types of cancer." (PMID 34103026, 2021).
Hypertension (1 paper, 2021). The presence of chronic increased pressure in the systemic arterial system. "Although the present study suggests kidney failure-associated DIDO1-Ab, hypertension-related FOXJ2-Ab, and DM-related CPSF2-Ab markers as risk factors of AIS, further study using the increasing number of specimens is needed to verify the suggestion." (PMID 34103026, 2021). "Serum DIDO1-Ab, FOXJ2-Ab, and CPSF2-Ab appear to be useful for diagnosing AIS and may originate from kidney disease, hypertension, and DM, respectively." (PMID 34103026, 2021).
mastitis (1 paper, 2024). Inflammation of breast tissue during lactation or postpartum due to an obstructed duct or infection. "The m6A modification gene FTO showed significant effects on the expression of m6A and other RMRGs (such as NSUN2, CPSF2, and METTLE), indicating complex co-expression relationships among different RNA modifications in the regulation of bovine S. aureus mastitis." (PMID 38271969, 2024).
pulmonary hypertension (1 paper, 2021). Increased pressure within the pulmonary circulation due to lung or heart disorder. "Serum CPSF2-Ab levels were correlated with aortic hypertension but not with pulmonary hypertension such as CTEPH and PAH." (PMID 34103026, 2021).
rheumatoid arthritis (1 paper, 2021). A chronic, systemic autoimmune disorder characterized by inflammation in the synovial membranes and articular surfaces. "Serum CPSF2-Ab levels were higher in patients with rheumatoid arthritis (but not in those with Sjögren’s syndrome, SLE, or ulcerative colitis) than in HDs." (PMID 34103026, 2021).
thyroid cancer (1 paper, 2021). "CPSF2 has a suppressive role in cell invasion in thyroid cancer and cancer stem cell population." (PMID 34103026, 2021).
tumor (5 papers, 2021 to 2025). "Scatter plots revealed that CLP1, CPSF2, and NUDT21 expressed significantly higher in tumor tissues than in normal gastric tissues, which was completely consistent with the results of the TCGA database." (PMID 36874129, 2023). "Analyses of public CRC databases revealed that both CPSF2 and CSTF3 were upregulated in tumor tissues compared with paired NCTs, and higher CPSF2 and CSTF3 expression was associated with worse survival." (PMID 36376892, 2022). "Lower levels of CPSF2 expression in the invasive area of PTC were reported in the literature when correlated with the central part of the tumor; however, this difference was not statistically significant." (PMID 36672561, 2022).
cancer (4 papers, 2021 to 2025). A tumor composed of atypical neoplastic, often pleomorphic cells that invade other tissues. "Thus, CPSF2-Abs may be associated indirectly with some types of cancer." (PMID 34103026, 2021). "Notably, serum DIDO1-Ab and CPSF2-Ab levels were not significantly different between HDs and patients with any type of cancer." (PMID 34103026, 2021). "However, how CPSF2 and CSTF3 regulate the stability of DLGAP1-AS2 is not clear, and whether the regulatory mechanism could be validated in other cancer types also remains to be elucidated." (PMID 36376892, 2022).
infection (2 papers, 2012 to 2015). The state of being infected such as from the introduction of a foreign agent such as serum, vaccine, antigenic substance or organism. "Several infection-induced SUMO targets also are involved in mRNA maturation events, such as 3′ end pre-mRNA processing (CPSF1, CPSF2, FIP1L1, RBBP6, and WDR33), splicing (CLASRP, SFPQ, and ZRANB2), and nuclear RNA quality control (ZC3H18, ZCCHC7, and PAPD5)." (PMID 26549460, 2015).
CPSF2 also shares sentences with these, for which no sentence is quoted: prostate carcinoma (2 papers); acute myocardial infarction (1); autoimmune disease (1); colorectal carcinoma (1); gastric cancer (1); hepatocellular carcinoma (1); ischemic stroke (1); kidney disease (1); kidney failure (1); pancreatic cancer (1); Papillary Thyroid Cancer (1); pulmonary diseases (1); Sjögren’s syndrome (1); Stroke (1); ulcerative colitis (1); viral infection (1).